BIRC2 (baculoviral IAP repeat containing 2)
Diseases named in the same sentence as BIRC2 in open-access papers (continued):
Sharing a sentence is not in itself a finding about the gene and the disease.
tumor (continued). "Since YAP/TAZ induce the transcription of anti-apoptotic and proliferation-associated genes, such as BIRC5/surviving, BIRC2/cIAP1, and MCL1, Hippo signaling activation results in tumor suppression." (PMID 33255245, 2020). "Three of these genes, apoptosis inhibitors BID, BIRC2 and BIRC3 were found in the differential expression analyses, being overexpressed in CTNNB1-mutated tumours." (PMID 31000732, 2019). "AMPA specifically decreases BIRC2 expression to activate caspase 3, leading to apoptosis of the tumor cells." (PMID 26840261, 2016). "The genomic instability of the miR-34a-high tumor cell line was reflected in high-copy amplicons coding for the oncogenes Yap1, Birc2, Birc3, Dcun1d5 (all on 9A1) or the leptin receptor (4C6)." (PMID 26871287, 2016). "Recently, Roepman and coworkers reported that cluster B genes IL6, IL8, YAP1, and BIRC2 are upregulated in metastatic HNSCC tumor specimens." (PMID 17498291, 2007). "Thus, Immunohistochemistry analysis of tumor sites revealed higher expressions of BIRC2/cIAP1 and Beclin-1 in PanNET patients compared to healthy controls." (PMID 38596136, 2024). "Based on this mechanism, suppression of NAP1L1 may inhibit tumour progression in patients with HCC with high protein expression of NAP1L1 or BIRC2." (PMID 38538582, 2024). "Finally, RNAscope in situ hybridisation (ISH) analysis further confirmed the presence of distinct transcripts (Socs2, Srsf2, Birc2) in endothelial cells associated with MES-GSC-driven and EGFR expressing tumours." (PMID 38570528, 2024). "Baculoviral IAP repeat-containing 2 (BIRC2) inhibits apoptosis by binding to tumour necrosis factor receptor-associated factors and has been identified as a key driver of aberrant proliferation, multidrug resistance and immune escape of tumour cells." (PMID 38538582, 2024). "BIRC2 plays a crucial role as an apoptosis inhibitor during tumour cell development." (PMID 38538582, 2024). "In this study, BIRC2 was identified as a direct target of BRD7, which functions as a transcriptional regulatory factor to inhibit carcinogenesis and tumor progression at least partially by negatively regulating the enhancer activation and expression of BIRC2 in NPC." (PMID 36788209, 2023). "Moreover, BIRC2 promoted cell proliferation, migration, invasion as well as xenograft tumor growth and metastasis in vivo, thus functioning as an oncogene in NPC." (PMID 36788209, 2023). "Moreover, functional analysis indicates that BIRC2-3 are promising, tumor-cell specific druggable targets in FA-HNSCC cells with the 11q22.2 amplification." (PMID 34997070, 2022). "Genetic loss of TNF and its death-signaling molecules (e.g., Tnfr1 and Casp8) led to uncontrolled tumor growth, whereas loss of molecules involved in ubiquitinating RIPK1 (e.g., Traf2 and Birc2/3) resulted in tumor rejection following immune checkpoint blockade." (PMID 34752416, 2021). "BIRC2 inhibition was more prominent when LCL161 was used in a xenograft tumor model." (PMID 34681681, 2021). "The BIRC2 gene is overexpressed in radiation-resistant tumor cells." (PMID 33673050, 2021). "Since BIRC2 and BIRC3 are adjacent, paralogous genes on human chromosome 11, it is not surprising that overexpression of cIAP2 has also been associated with the progression of the same tumor types and with treatment resistance." (PMID 29167558, 2017). "In complementary work, a tumor cell line that was selected for resistance to immunotherapy upregulated AKT compared with sensitive wild-type cells, and this was associated with increased levels of BIRC2 and BIRC3, BCL-2 and BCL-XL." (PMID 29163772, 2017). "Molecular profiling of transformed and metastatic murine SCCs showed that Gro1 (IL8 homolog), antiapoptotic gene cIAP-1 (cIap-1/Birc2), and Yap65 (YAP 1) were upregulated and clustered together in association with activation of NF-κB and tumor growth, metastatic progression, and angiogenesis." (PMID 17498291, 2007).
tumor (continued). "The overexpression of the BIRC2 gene may promote tumor growth in U87-MG through siHMOX1 treatment." (PMID 40739397, 2025). "Moreover, BIRC2 was found to function as an oncogene in NPC, promoting cell proliferation, migration, and invasion as well as xenograft tumor growth and metastasis in vivo, and restoration of BIRC2 expression rescued the inhibitory effect of BRD7 on the malignant phenotype of NPC." (PMID 36788209, 2023). "Here, (R,S′)-MNF exerted a potent repression of the Hippo-YAP/TAZ signaling in PANC-1 tumor xenografts with the downregulation of genes encoding key mediators (TAOK1, MST2, MOBK1B), transcriptional regulators (WWTR1, TEAD4), and downstream pro-survival genes CYR61, BIRC2, and MCL1." (PMID 35256673, 2022). "Predictably, pharmacologic targeting of BIRC2 and BIRC3 will not only induce GBM tumor apoptosis but should also impact the TME as a whole." (PMID 40616096, 2025). "Knockdown of NAP1L1 promoted the ubiquitin-mediated degradation of BIRC2 through the ubiquitin–protein junction of UBR4, which in turn inhibited the proliferation and apoptotic escape of HCC cells and exerted anti-tumour effects." (PMID 38538582, 2024). "The results indicated that NAIP, BIRC2, BIRC3, XIAP, BIRC5, and BIRC6 showed significantly higher expression levels in tumor tissues than in normal tissues." (PMID 37781078, 2023). "Especially, BIRC2 has been reported as a hypoxia-induced gene that impairs CD8 + T and NK cell-mediated killing of tumor cells." (PMID 36788209, 2023). "In BC cells, hypoxia induces the expression of BIRC2, which counters the capability of CXCL9 to recruit CD8+ T cells and NK cells to the tumor, and hence increases tumor growth and resistance to anti-PD-1 therapy." (PMID 36834641, 2023). "The levels of NAIP, BIRC2, XIAP, and BIRC6 were significantly elevated in the subgroups of tumor stages 1-3 compared to their levels in the normal subgroups, with no discernible differences in their levels in the subgroup of tumor stage 4." (PMID 37781078, 2023). "In melanoma and breast cancer cells, hypoxia induces HIF-dependent expression of BIRC2, which inhibits expression of CXCL9, thereby blocking recruitment of NK and CD8+ T cells to the tumor, leading to increased tumor growth and resistance to anti–PD-1 therapy." (PMID 35642641, 2022). "From TCGA datasets, FADD, BIRC2/3, TNFSF10, and TNFRSF10B/C/D were overexpressed in tumor cases compared to normal." (PMID 33737574, 2021). "We observed that the BIRC2, BIRC3, BIRC5, and BIRC7 genes showed the increased levels of expression in tumor tissue compared to normal tissue, while in the case of the BIRC1, BIRC4, BIRC6, and BIRC8 genes, we saw the decreased expression levels." (PMID 33673050, 2021). "Compared to the NCI60 analysis, we further revealed distinct expression pattern of BIRC5 and BIRC7 and synchronized expression for NAIP, BIRC2, BIRC3, XIAP and BIRC6 in multiple tumor types." (PMID 31964418, 2020). "Although NAP1L1 can induce the apoptotic escape of tumour cells, whether it determines the progression of HCC by affecting the stability of BIRC2, a key factor in apoptotic escape, remains unclear." (PMID 38538582, 2024). "In the HNSCC tumour microenvironment (TME), our data indicate that the IAP family members, including BIRC2, may affect immune response." (PMID 38364254, 2024). "Tumour progression may be inhibited by suppressing NAP1L1 expression in patients with HCC with high protein expression of NAP1L1 and BIRC2." (PMID 38538582, 2024). "The BIRC2 expression in HNSCC samples was studied by qRT-PCR, and 12 HNSCC tissue specimens exhibited a much higher relative expression level of BIRC2 than corresponding nearby non-tumour tissue samples, according to the findings (P < 0.05)." (PMID 38364254, 2024).
tumor (continued). "Recently, we have investigated the anti-tumor effects of birinapant in HPV(−) HNSCC cells, and observed that cells retaining FADD/BIRC2 amplification and overexpression were sensitive to birinapant, and the effects were enhanced by death agonists TNFα or TRAIL23." (PMID 33737574, 2021). "This difference could be attributed to the downregulation of their potential targets (e.g., BIRC2 baculoviral IAP repeat containing 2 (cIAP1) and MCL1 apoptosis regulator (MCL1)), important in tumor cell survival following TKI treatment." (PMID 34830398, 2021). "Our transcriptome sequencing results identified several DEGs involved in cell adhesion, such as BIRC2, BIRC3, and MLCK, which could influence tumor invasion or metastasis." (PMID 28114404, 2017). "Adjacent tumour suppressor pairs (e.g., CDKN2A/CDKN2B, BIRC2/BIRC3, HELQ/FAM175A...) may be especially rewarding targets for homozygous deletion in some cases, as two mutation events can abolish all tumour suppressor activity." (PMID 29089486, 2017). "Interestingly, based on our results, BIRC2 expression did not correlate with either tumor purity or most of the immune cell infiltration, and only showed weak negative correlation with CD8+ T cell infiltration (Rho = − 0.234, p = 1.31 × 10− 6)." (PMID 40616096, 2025). "Collectively, these findings suggest that BIRC2 knockdown in A549 and LLC‐1 cells results in decreased gene expression, inhibited proliferation, reduced clonogenic ability, and increased apoptosis, highlighting the critical role of BIRC2 in cell survival and tumour progression." (PMID 40159652, 2025). "Furthermore, the recovery of BIRC2 expression could rescue the inhibitory effect of BRD7 on cell proliferation, migration, invasion and xenograft tumor growth and metastasis." (PMID 36788209, 2023). "To ascertain that suppression of BIRC2 expression by BRD7 is responsible for BRD7’s tumor suppressor function in NPC tumorigenesis and tumor progression, we sought to determine whether the restoration of BIRC2 expression reverses the tumor-suppressive roles of BRD7 induced in vivo." (PMID 36788209, 2023). "Taken together, our findings proved that BRD7 functions as a tumor suppressor at least partially by inhibiting enhancer activity and the expression of BIRC2 in NPC, and targeting the BRD7/BIRC2 axis might provide a potential strategy for the diagnosis and treatment of NPC." (PMID 36788209, 2023). "BIRC2 and BIRC3 mRNA levels in tumor and paired non-tumor tissues in HNSCC patients were further analyzed." (PMID 39578442, 2024). "MAP3K14 (NIK1), BIRC2 (cIAP1), RIPK1, CASP7, CASP8, and TNF play an important role in inhibiting proliferation and invasion of tumor cells via the activation of the non-canonical NF-κB signaling pathway." (PMID 34638912, 2021). "The combination of birinapant and irradiation or irradiation alone also significantly inhibited tumor growth in UM-SCC-11B xenografts overexpressing FADD and BIRC2, but not in UM-SCC-1 xenografts showing weaker growth and FADD/BIRC2 copy expression and heterozygous CASP8 mutation." (PMID 39458950, 2024). "We found that c-IAP1 (Birc2), XIAP (Birc4), Survivin (Birc5) and Livin (Birc7) were overexpressed in ESCC tissues, while NAIP (Birc1) and c-IAP2 (Birc3) were comparable between tumor tissues and adjacent non-tumor tissues." (PMID 25216531, 2014). "For this gene in particular, we validated that different tumor cell lines may indeed not all be equally dependent on TRAF2 for their immune resistance, with some cell lines relying (more) on BIRC2, whereas others require inactivation of both genes in order to be sensitized to T cell challenge." (PMID 37398651, 2023).
infection (28 papers, 2009 to 2025). The state of being infected such as from the introduction of a foreign agent such as serum, vaccine, antigenic substance or organism. "During pathogenic infection, BIRC2 and BIRC3 promote host survival by preventing death-receptor-induced programmed necrosis in immune and non-immune cells." (PMID 34887869, 2021). "During pathogen infection, BIRC2 and BIRC3 inhibit apoptosis by ubiquitination and promoting proteasomal degradation." (PMID 38891754, 2024). "As in HFFF-TERTs, infection of THP-1 macrophages also promoted downregulation of cIAP1 (BIRC2), a key regulator of the TNF-dependent extrinsic pathway of apoptosis." (PMID 38065956, 2023). "Infection by H. pylori led to a striking albeit transient up-regulation of BIRC2, BIRC3 and BCL2A1." (PMID 35089437, 2022). "Furthermore, anti-apoptotic genes, GADD45B and CFLAR, and the IAP family members (BIRC2 and BCL2L1) were upregulated early or late after DTMUV infection." (PMID 32897243, 2020). "Compared with the control group without E. piscicida infection, the expression of BIRC2 in zebrafish larvae infected with E. piscicida had no significant change at 6 and 24 hpi during the early stage of infection, but significantly increased at 72 hpi during the late stage of infection." (PMID 34887869, 2021). "Infection of AGS cells with H. pylori for 1 h dramatically increased the expression of BIRC3 (gene of cIAP2), but not the expression of BIRC2 (gene of cIAP1), BIRC4 (gene of XIAP), BIRC5 (gene of Survivin) and other apoptosis related genes." (PMID 32820150, 2020). "Many genes associated with the cell death such as tumour necrosis factor receptor (Tnfrsf1a), inhibitor of kappaB kinase (Ikbkg), kinases (Cd82 and Cdk2), and apoptosis regulator (Bcl2l1 and Birc2) were only up-regulated in WT infection and showed no expression in BM16 infection." (PMID 27634329, 2016).
adenocarcinoma (2 papers, 2016 to 2024). A common cancer characterized by the presence of malignant glandular cells. "Inasmuch as TNFα-NFκB pathway was enriched in KEAP1 R320 and R470 adenocarcinoma samples in our GSEA analysis, we analyzed the expression of two NFκB target genes, IL23A and BIRC2, in transduced cells." (PMID 38184997, 2024).
bacterial infection (2 papers, 2009 to 2021). "The present study confirms that the antiapoptotic protein BIRC2 negatively regulates bacterial infection, which is consistent with our recent report showing that proapoptotic protein BID positively regulates bacterial infection." (PMID 34887869, 2021). "The role of mammalian BIRC2 in bacterial infection was also observed." (PMID 34887869, 2021). "Based on this and our study, it is possible that piscine BIRC2 is involved in the regulation of immune responses mediated by NOD1 and NOD2 signaling in response to bacterial infection." (PMID 34887869, 2021).
BIRC2 also shares sentences with these, for which no sentence is quoted: colon carcinoma (16 papers); pancreatic cancer (16); glioblastoma (10); osteosarcoma (10); bladder cancer (9); head and neck squamous cell carcinoma (9); glioma (7); gallbladder cancer (6); neuroblastoma (6); rhabdomyosarcoma (6); acute myeloid leukemia (4); triple-negative breast carcinoma (4); breast tumor (3); Oral Squamous Cell Carcinoma (3); Arthritis (2); asthma (2); cervical squamous cell carcinoma (2); chronic lymphocytic leukaemia (2); colitis (2); colorectal tumors (2); esophageal cancer (2); non-small cell lung carcinoma (2); rectal cancer (2); serous ovarian cancer (2); Stroke (2); systemic inflammatory response syndrome (2); T-cell lymphoma (2); thymoma (2); thyroid cancer (2); acute tubular necrosis (1).
A further 66 diseases each share a sentence with BIRC2 in 1 paper.